LIMK1 (LIM domain kinase 1)
Description:
Serine/threonine-protein kinase that plays an essential role in the regulation of actin filament dynamics. Acts downstream of several Rho family GTPase signal transduction pathways. Activated by upstream kinases including ROCK1, PAK1 and PAK4, which phosphorylate LIMK1 on a threonine residue located in its activation loop. LIMK1 subsequently phosphorylates and inactivates the actin binding/depolymerizing factors cofilin-1/CFL1, cofilin-2/CFL2 and destrin/DSTN, thereby preventing the cleavage of filamentous actin (F-actin), and stabilizing the actin cytoskeleton. In this way LIMK1 regulates several actin-dependent biological processes including cell motility, cell cycle progression, and differentiation. Phosphorylates TPPP on serine residues, thereby promoting microtubule disassembly. Stimulates axonal outgrowth and may be involved in brain development. [Isoform 3]: Has a dominant negative effect on actin cytoskeletal changes. Required for atypical chemokine receptor ACKR2-induced phosphorylation of cofilin (CFL1).
Synonyms: LIMK-1; LIMK
Tractability: Small molecule: a structure with a bound ligand is known; a high-quality ligand is known; it belongs to a druggable protein family. PROTAC: it is named in the literature on targeted protein degradation; UniProt records ubiquitination sites on it; ubiquitination databases record sites on it; its protein half-life has been measured; a small molecule that binds it is known.
Target class: Kinase; TKL protein kinase group; Protein Kinase; TKL protein kinase LISK family; TKL protein kinase LIMK subfamily; Enzyme
Chemical probes: SM311 (high quality), TH257 (high quality)
Gene: Protein-coding gene on chromosome 7 (74,082,933 to 74,122,527, forward strand). Ensembl gene ENSG00000106683.
Subcellular location: Cytoplasm; Nucleus; Cytoplasm, cytoskeleton; Cell projection, lamellipodium
Subcellular location (Human Protein Atlas): Cytosol; Nuclear speckles
Pathways (Reactome):
Developmental Biology: EPHB-mediated forward signaling; Sema3A PAK dependent Axon repulsion; Sema4D induced cell migration and growth-cone collapse
Signal Transduction: RHO GTPases Activate ROCKs; RHO GTPases activate PAKs
Immune System: Regulation of actin dynamics for phagocytic cup formation
Gene Ontology:
Molecular function: heat shock protein binding; protein binding; protein serine kinase activity; protein serine/threonine kinase activity; ubiquitin ligase inhibitor activity; ubiquitin protein ligase binding; protein kinase activity; ATP binding
Biological process: positive regulation of actin filament bundle assembly; protein phosphorylation; actin cytoskeleton organization; Fc-gamma receptor signaling pathway involved in phagocytosis; nervous system development; positive regulation of axon extension; positive regulation of stress fiber assembly; Rho protein signal transduction; signal transduction
Cellular component: cytoplasm; cytosol; glutamatergic synapse; nuclear speck; nucleus; postsynapse; lamellipodium; neuron projection; cell junction; cytoskeleton; focal adhesion; membrane
Genetic constraint (gnomAD): Loss-of-function variants: 15 observed, 68.39 expected, observed/expected ratio (o/e) 0.22, 90% interval 0.15 to 0.34. The upper end of that interval is the gene's LOEUF score, 0.34, which puts it in group 1 of 6, group 1 being the genes least tolerant of losing a copy. Missense variants: 666 observed, 859.79 expected, observed/expected ratio (o/e) 0.77, 90% interval 0.73 to 0.83. Synonymous variants: 353 observed, 356.54 expected, observed/expected ratio (o/e) 0.99, 90% interval 0.91 to 1.08.
Homologues: Orthologues: macaque LIMK1 (99% identical), pig LIMK1 (98% identical), chimpanzee LIMK1 (98% identical), rat Limk1 (95% identical), mouse Limk1 (95% identical), guinea pig LIMK1 (95% identical), dog LIMK1 (95% identical), rabbit LIMK1 (93% identical), zebrafish limk1a (73% identical), tropical clawed frog limk1 (72% identical), zebrafish limk1b (54% identical). Paralogues in human: LIMK2 (53% identical), LRRK2 (25% identical), TESK2 (22% identical), TNNI3K (22% identical), TESK1 (22% identical), BRAF (18% identical), KSR2 (18% identical), KSR1 (17% identical), MAP3K9 (17% identical), RAF1 (17% identical), MAP3K10 (16% identical), MAP3K21 (16% identical), and 11 more.
Diseases named in the same sentence as LIMK1 in open-access papers:
LIMK1 is named in the same sentence as 151 diseases in open-access papers, as found by Europe PMC text mining. Sharing a sentence is not in itself a finding about the gene and the disease. The quoted sentences say what the papers report.
breast carcinoma (50 papers, 2007 to 2025). "Recently, a ROCK: LIMK1 pathway was implicated in the co-ordination of cofilin activity at the plasma membrane of invasive rat mammary carcinoma cells." (PMID 18852895, 2008). "For instance, lncRNA Lnc-408 promotes invasion and metastasis of breast cancer cells by regulating the miR-654-5p/LIM kinase 1 (LIMK1) axis, highlighting the intricate interplay among lncRNAs, miRNAs, and mRNAs in the breast cancer regulation." (PMID 41029829, 2025). "In summary, these data indicate that MEX3A can enhance RhoA/ROCK1/LIMK1 signaling in breast cancer cells." (PMID 34486491, 2021). "In line with our discovery, LIMK1 has been shown to promote progression of multiple cancers including breast cancer, colorectal cancer, ovarian cancer, by inducing cell proliferation, migration or invasion." (PMID 33883692, 2021). "For instance, miR-128-3p functions as a tumor suppressor and triggers cell cycle arrest by repressing LIMK1 expression in breast cancer; downregulation of miR-34a reduces HCC metastasis." (PMID 34376644, 2021). "Overall, our study concluded that MEX3A promotes its migration and proliferation in breast cancer cells via modulating RhoA/ROCK1/LIMK1 signaling pathway." (PMID 34486491, 2021). "For instance, miR-128-3p overexpression reduces cell proliferative, migratory and invasive potential and hampers cell cycle progression through targeting LIM domain kinase 1 in breast cancer." (PMID 34493213, 2021). "For example, overexpression of LIMK1 in carcinoma cells significantly promotes cofilin phosphorylation, which then abolishes cancer cell motility to decrease invasion and metastasis in breast cancer." (PMID 32983407, 2020). "For example, it was reported that miR-128-3p suppressed breast cancer progression by targeting LIM domain kinase 1(LIMK1)." (PMID 32178675, 2020). "Increasing evidence showed that Limk1 was a biomarker of squamous cell carcinoma, lung cancer, breast cancer, and even GBM." (PMID 33062725, 2020). "LIMK1 levels are demonstrated to be increased in some human cancers, and upregulation of LIMK1 leads to tumor progression in prostate and breast cancer cells." (PMID 31541994, 2019). "The inhibition of LIMK1 activity was found to be able to reduce breast cancer growth and invasiveness, indicating the important role of LIMK1 in breast cancer metastasis." (PMID 27625789, 2016). "LIMK1 overexpression has been noted in breast cancer progression, while paxillin overexpression has been shown to enhance breast cancer metastasis." (PMID 27769065, 2016). "Abundance of the LIMK1 protein and mRNA was reduced in two out of three breast cancer cell lines, but was unchanged in a third one." (PMID 26203557, 2015). "When LIMK1 is overexpressed in breast cancer cells, increased invasion and metastasis of breast cancer cells are promoted." (PMID 25237832, 2014). "Role of LIMK1 in promoter activation has been reported earlier, which showed that LIMK1 expression increased activation of uPA promoter in breast cancer cells." (PMID 21219645, 2011). "Taken together, these data demonstrate that LIMK1 activity in both the cytoplasmic and nuclear compartments promotes breast cancer progression, underscoring that nuclear LIMK1 contributes to the transforming function of LIMK1." (PMID 21682918, 2011). "The data presented here reveal that LIMK1 is expressed in both the cytoplasmic and nuclear compartments in human breast cancer specimens, and that LIMK1 in either cytoplasmic or nuclear compartments contributes to mammary epithelial cell tumorigenesis." (PMID 21682918, 2011). "LIMK1 levels are increased in several human cancers, with LIMK1 over-expression in prostate and breast cancer cells leading to tumor progression." (PMID 21682918, 2011). "Functional studies have found that increasing LIMK1 expression in human breast cancer cell lines results in increased cellular invasion and xenograft tumor growth." (PMID 21682918, 2011).
breast carcinoma (continued). "In sum, these studies reveal that LIMK1 has important cytoplasmic and nuclear functions that contribute to breast cancer progression." (PMID 21682918, 2011). "LIMK1 expression increased invasiveness of non-invasive prostate and breast cancer cells and expression of antisense RNA or dominant negative kinase-dead LIMK1 greatly reduced invasion of prostate and breast cancer cells." (PMID 21219645, 2011). "For example, expression of dominant-negative LIMK1 in breast cancer cell lines resulted in suppression of matrigel invasion in vitro, and inhibition of liver, lung and bone metastasis in vivo." (PMID 21682918, 2011). "Accordingly, earlier studies including ours clearly demonstrated an important role of LIMK1 in induction of invasion and metastasis of prostate and breast cancer cells and tumors." (PMID 21219645, 2011). "The results of our in vitro studies revealed that both cytoplasmic and nuclear localized LIMK1 can impact the aggressiveness of human breast cancer cells." (PMID 21682918, 2011). "Recently, a novel role for LIMK1 as an oncogene has been demonstrated in prostate and breast cancer cells." (PMID 17559677, 2007). "LIMK1 and LIMK2 have been reported to be overexpressed in breast cancer, and there is growing evidence of their implication in molecular pathways with interactors linked to breast cancer tumorigenesis." (PMID 36899941, 2023). "It has been reported that Lnc-408 upregulates LIMK1 signaling pathway via sponging miR-654-5p, thereby accelerating breast cancer metastasis and invasion, and Lnc-MT1JP has been proved to enhance the resistance of hepatocellular carcinoma cells to Lenvatinib via sponging miR-24-3p." (PMID 35012431, 2022). "CAPN2 might be an important target with therapeutic potential for the design of inhibitors of the LIMK1/CFL1 signaling pathway in breast cancer." (PMID 34381117, 2021). "Finally, we assessed the MEX3A dependent regulation of RhoA/ROCK1/LIMK1 signaling pathway involved in the progression of breast cancer." (PMID 34486491, 2021). "Given the importance of PAK1 and LIMK1 in breast cancer metastasis, we examined whether the PAK1/LIMK1/Cofilin1 signaling pathway is the downstream signaling cascade of SphK2/S1P." (PMID 33968977, 2021). "Finally, high expression of CAPN2 and aberrant activation of the LIMK1/CFL1 axis found in breast cancer have been positively correlated with cancer development and metastasis." (PMID 34381117, 2021). "Also, the phosphorylation of RhoA, ROCK1 and LIMK1 in breast cancer cells is positively regulated by MEX3A." (PMID 34486491, 2021). "LIMK1 overexpression could increase the invasiveness of breast and prostate cancer cells both in vitro and in vivo, and knockdown of LIMK1 could diminish invasion of breast carcinoma and prostate carcinoma cells." (PMID 33126409, 2020). "And Limk1 knockdown induced the antitumor effects for lung cancer, breast cancer, or even GBM." (PMID 33062725, 2020). "Taking into account the fact that MT1-MMP and LIMK1/2 are overexpressed in cancers, in particular breast cancers, our study provides novel insights at the mechanisms regulating tumor cell invasion in a 3D context and suggest new possibilities for therapeutic interventions." (PMID 27116935, 2016). "In contrast, the increased activity of LIMK1 led to human breast cancer progression." (PMID 28025492, 2016). "As a member of the LIM kinase (LIMK) family widely involved in cell motility and invasion, the overexpression of LIMK1 was found to increase the motility of human breast cancer cell lines and was found to prompt tumor angiogenesis and induce metastasis to the livers and lungs in breast cancer." (PMID 27625789, 2016). "In breast cancer cells, PAK4 inhibits cell adhesion and promotes cell migration by selectively inducing αvβ5 mediated breast cancer cell motility through the phosphorylation of the integrin β5 cytoplasmic tail and by regulating actin depolymerisation through phosphorylation of LIMK1." (PMID 26554417, 2015).
breast carcinoma (continued). "Overexpression of active LIMK1 inhibits the motility of mammary cancer cells." (PMID 23112838, 2012). "Within this subset of strongly cytoplasmic stained tissues, 52% of the strongly cytoplasmic stained breast cancer tissues also expressed nuclear LIMK1, whereas only 27% of the corresponding strong cytoplasmic stained normal breast tissue also expressed nuclear LIMK1." (PMID 21682918, 2011). "LIM kinase 1 (LIMK1) is an actin and microtubule cytoskeleton modulatory protein that is overexpressed in a number of cancerous tissues and cells and also promotes invasion and metastasis of prostate and breast cancer cells." (PMID 21219645, 2011). "In this study, we sought to determine whether cytoplasmic and/or nuclear LIMK1 localization has a pro-tumorigenic activity in breast cancer cells." (PMID 21682918, 2011). "Recent studies have indicated an important role of LIMK1 in growth and invasion of prostate and breast cancer cells; however, the molecular mechanism whereby LIMK1 induces tumor progression is unknown." (PMID 17559677, 2007). "While reports on LIM domain kinase 1 (LIMK1) in PCa specimens are limited, it may be a promising marker, as in many other cancers are LIMK1-positive, including colorectal cancer, lung cancer, osteosarcoma, and breast cancer, which also has clinical implications." (PMID 37371647, 2023). "Therefore, we investigated whether MEX3A affected RhoA/ROCK1/LIMK1 signaling in breast cancer cells." (PMID 34486491, 2021). "In addition, we determined that MEX3A could activate RhoA/ROCK1/LIMK1 signaling in the breast cancer cells." (PMID 34486491, 2021). "Thus, we first performed IHC analysis of LIMK1 expression in normal and malignant human breast specimens and found that LIMK1 expression is increased in both subcellular compartments in human breast cancer, with nuclear levels being highest in those tumors displaying strong cytoplasmic staining." (PMID 21682918, 2011). "Accordingly, overexpression of LIMK1 in breast cancer cell lines MCF-7 and MDA-MB-231 increased their motility, while inhibition of LIMK1 attenuated this effect." (PMID 34966720, 2021). "Moreover, miR-128-3p could participate in the progression of diver cancers through targeting different genes, and miR-128-3p regulated cell growth in breast cancer by targeting LIMK1 and overexpression of miR-128-3p in breast cancer patients presaged a good prognosis." (PMID 32377170, 2020). "Overexpression of LIMK1 suppressed EGF-induced membrane protrusion and locomotion in rat mammary carcinoma cells." (PMID 28025492, 2016). "For example, over-expression of LIMK1 in MDA-MB-231, MCF-7 and MDA-MB-435 human breast cancer cell lines resulted in increased cellular migration and invasion through Matrigel." (PMID 21682918, 2011). "Having demonstrated that LIMK1 can be expressed both cytoplasmically and nuclearly in human breast cancers, we next developed a model system to segregate GFP-tagged LIMK1 to the cytoplasm or the nucleus in MDA-MB-231 breast cancer cells." (PMID 21682918, 2011). "In contrast, inhibiting LIMK1 expression, or blocking LIMK1 activity, reduced the aggressive behavior of human MDA-MB-231 and MDA-MB-435 breast cancer cell lines." (PMID 21682918, 2011). "Our results point to a distinct function for LIMK1 and LIMK2 downstream of ROCK during breast cancer cell migration." (PMID 18852895, 2008). "We found that single knockdown of LIMK1 or LIMK2 triggered a strong decrease (about 80%) in matrix degradation without affecting MT1-MMP levels or expression of the other LIMK isoform in MDA-MB-231 cells and BT-549 breast cancer cells." (PMID 27116935, 2016). "This novel link between LIMK1/2 and MT1-MMP may have important consequences for therapeutic control of breast cancer cell invasion." (PMID 27116935, 2016). "LIMK1, a unique serine/threonine kinase containing two N-terminal LIM domains in tandem and a PDZ domain is a newly identified candidate that promotes prostate and breast cancer metastasis." (PMID 21219645, 2011).
breast carcinoma (continued). "Indeed, LIMK1 and LIMK2 have been shown to be upregulated in breast cancer, gastric cancer, prostate cancer, and malignant melanoma cells, and they seem to be involved in multiple non-canonical signalling pathways that, when dysregulated, actively participate in tumorigenesis." (PMID 36899941, 2023).